SMAD4 (SMAD family member 4)
Diseases named in the same sentence as SMAD4 in open-access papers (continued):
Sharing a sentence is not in itself a finding about the gene and the disease.
liver fibrosis (continued). "Here, to explore the functional role of hepatocyte Smad4 and the molecular mechanism in liver fibrosis, a CCl4-induced liver fibrosis model was established in mice with hepatocyte-specific Smad4 deletion (Smad4Δhep)." (PMID 36232998, 2022). "In carbon tetrachloride (CCl4)-induced hepatic fibrosis mice, miR-34a imbalance was also found to promote liver fibrosis via targeting Smad4 and activation TGF-β1/Smad3 pathway." (PMID 35795649, 2022). "Western blotting analysis of Smad4 expression in liver tissues revealed that Smad4 expression was significantly upregulated in mice with liver fibrosis compared with control mice." (PMID 36232998, 2022). "Taken together, these findings suggested that Smad4 knockout in hepatocytes attenuated CCl4-induced liver fibrosis." (PMID 36232998, 2022). "Consistently, double immunofluorescence staining further indicated that Smad4 was highly expressed in hepatocytes in liver fibrosis tissues." (PMID 36232998, 2022). "Here, we used a mouse model of hepatocyte-specific Smad4 deletion to explore its role and molecular mechanism in liver fibrosis." (PMID 36232998, 2022). "In this study, we found that the expression of ID1 and CTGF in hepatocytes was markedly downregulated in hepatocyte-specific Smad4 deletion mice with liver fibrosis." (PMID 36232998, 2022). "Together, our findings support this conclusion and demonstrate that hepatocyte-specific Smad4 deletion reduces CCl4-induced liver fibrosis." (PMID 36232998, 2022). "The expression level of Smad4 in hepatocytes of advanced liver fibrosis stage was higher than that in hepatocytes of early liver fibrosis stage." (PMID 36232998, 2022). "Inhibition of SMAD3 decreased collagen I expression while Smad2 increased collagen I expression, and Smad4 is crucial in liver fibrosis by supporting SMAD3 activity." (PMID 36482069, 2022). "Collectively, these results demonstrated that Smad4 expression was significantly enhanced in hepatocytes during the progression of liver fibrosis." (PMID 36232998, 2022). "In this study, we established a mouse model of hepatocyte-specific Smad4 deletion to explore the functional role and molecular mechanism of Smad4 in liver fibrosis." (PMID 36232998, 2022). "In conclusion, our research indicated that Smad4 expression in hepatocytes is closely involved in the development of liver fibrosis." (PMID 36232998, 2022). "Together, our findings demonstrated that Smad4 expression in hepatocytes can promote fibrosis during the pathogenesis of early hepatic fibrosis." (PMID 36232998, 2022). "The inhibition of phosphorylation of Smad2/3 and Smad4 prevents the downstream signaling pathway, which is responsible for liver fibrosis." (PMID 32365537, 2020). "Conversely, hepatic expressions of TGF-β1, α-SMA, Col-1, and Smad4 were further increased by the treatment with ZnPP as compared with those of MCD-induced steatohepatitis-related liver fibrosis." (PMID 32461992, 2020). "The expressions of p-Smad2/3 and Smad4 were markedly increased in hepatic fibrosis mice compared with normal mice (p < 0.05)." (PMID 30103395, 2018). "Activation of HSC by TGF-β plays a key role in liver fibrosis at the early phase and the activated cells are accompanied with high accumulation of p-Smad2/3 and Smad4 in cell nucleus." (PMID 28384213, 2017). "This function in TGF- β signaling suggests that SMAD4 can be considered as a target for controlling HSCs activation during liver fibrosis." (PMID 26468346, 2015). "Based on our results, we suggest that BCAA improves liver fibrosis by downregulating Smad-4, TIMP-1, and Col1α2 through the inhibition of TGF-β1." (PMID 24223741, 2013). "Our research results show that GA ameliorates E.granulosus infection-mediated hepatic fibrosis by specifically inhibiting SUMOylation of Smad4 in macrophages through targeted modulation of the SUMOylation pathway, thereby hindering pathogenic macrophage-hepatic stellate cell crosstalk." (PMID 41529030, 2026).
liver fibrosis (continued). "SMAD4 is not only the target gene of miR-324-3p, but also plays a role in liver fibrosis." (PMID 38407690, 2025). "MSC-derived exosomal miR-618 dampens the development of liver fibrosis by targeting Smad4." (PMID 38756248, 2024). "Furthermore, TPLR inhibited TGF-β/Smad pathway ameliorating hepatic fibrosis though downregulation the expression of Smad2/3, Smad4, and upregulation the expression of Smad7 in vivo and in vitro." (PMID 36829153, 2023). "Taken together, our results clearly demonstrate that the Smad4 expression in hepatocytes plays an important role in promoting liver fibrosis and could therefore be a promising target for future anti-fibrotic therapy." (PMID 36232998, 2022). "In addition, Smad4 plays a pivotal role in the switch of TGF-β function in liver fibrosis and inflammation." (PMID 36232998, 2022). "Although many studies have investigated the role of Smad4 in liver diseases, the function and mechanism of hepatocyte Smad4 during early liver fibrosis remains unclear." (PMID 36232998, 2022). "Notably, we found that hepatocyte-specific Smad4 deletion alleviated CCl4-induced liver fibrosis and suppressed hepatocyte proliferation and EMT." (PMID 36232998, 2022). "Notably, Smad4 deletion in hepatocytes alleviated CCl4-induced liver fibrosis and decreased inflammatory cell infiltration in liver tissues." (PMID 36232998, 2022). "Collectively, these results indicated that Smad4 deficiency in hepatocytes decreased the expression of ID1 and CTGF, which may be involved in the process of liver fibrosis." (PMID 36232998, 2022). "However, we used CCl4 to induce short-term fibrosis, and the functional role of hepatocyte Smad4 in long-term liver fibrosis needs to be further studied." (PMID 36232998, 2022). "Moreover, decreased CCAT2 diminished liver fibrosis through preventing phosphorylated Smad2/3, Smad4 and TGF-β1 signaling." (PMID 36482069, 2022). "Additionally, studies have reported that Smad4-mediated signal transduction in different cell types plays different roles in liver fibrosis." (PMID 36232998, 2022). "Collectively, Smad4 may represent a potential candidate target for the prevention and targeted therapy in liver fibrosis." (PMID 36232998, 2022). "Moreover, previous reports have suggested that downregulation of miRNA-21 in HSCs alleviates liver fibrosis through overexpression of Smad7, and miRNA-454 directly targets Smad4 to inhibit the activation of HSCs." (PMID 36474240, 2022). "Meanwhile, we’ve noticed that there was a report indicating that HBV-encoded pX oncoprotein directly interacts with SMAD4, stabilizing the complex of SMAD4 with components of the basic transcriptional machinery and contributing to HBV-associated liver fibrosis." (PMID 34168644, 2021). "We further analyzed whether ARK5 could regulate TβRI and Smad4 during liver fibrosis." (PMID 36361872, 2022). "However, our study showed Smad4 was found increased at 4 wk p.i., and its expression decreased with the development of hepatic fibrosis, which suggested that the effects of Smad4 might occur at early and middle stage of hepatic fibrosis." (PMID 25649869, 2015). "In previous studies using murine models, the combined use of BCAAs attenuated liver fibrosis through inhibition of the TGF-β1 signaling pathway by downregulating several key pathway components, including SMAD-4, P-SMAD3L, TIMP-1, PDGFRβ, p-ERK, and COL1A2." (PMID 39495311, 2024). "A study has shown that H19 exacerbates liver fibrosis by interacting with miR-148a to induce overexpression of USP4, leading to activation of HSCs by inhibiting degradation of Smad4 or TGF-βRI and enhancing TGF-β signaling." (PMID 39195573, 2024). "SMAD2, SMAD3, SMAD4, and SMAD7 expression levels were measured to determine TGF-β1 related hepatic fibrosis." (PMID 39055873, 2024).
liver fibrosis (continued). "Studies have found that increasing the content of SMAD4 can reduce the synthesis of hepatic ECM, thus slowing down the process of liver fibrosis, which has potential clinical application value." (PMID 37446187, 2023). "To further elucidate the role of Smad4 in hepatocytes, we used siRNA to knock down Smad4 in AML-12 cells, and then the cells were treated with TGF-β1 for 12 h and 24 h to simulate liver fibrosis environment in vitro." (PMID 36232998, 2022). "According to the present study findings, RF can reduce liver fibrosis by altering TGF-β/Smad signaling by decreasing protein expression of Smad2/3 phosphorylation and Smad4 formation, which results in down-regulation of Col1A1 and α-SMA transcriptions." (PMID 35549741, 2022). "Studies have shown that some drugs, such as Ferulic acid, Yu Gan Long, and Magnesium Isoglycyrrhizinate, can inhibit the expression of Smad4 in TGF-β signaling pathway, thereby inhibiting liver fibrosis." (PMID 36232998, 2022). "However, the specific contribution of hepatocyte Smad4 during liver fibrosis remains unclear." (PMID 36232998, 2022). "Sma mothers against decapentaplegic homologue 4 (Smad4) is a key intracellular transcription mediator of transforming growth factor-β (TGF-β) during the development and progression of liver fibrosis." (PMID 36232998, 2022). "For example, miR-219 can modulate liver fibrosis by directly targeting tumor growth factor β receptor 2 (TGFBR2), while miR-34a-5p targets Smad4 and modulates TGF-β1/Smad3 pathway in HSCs to ameliorate liver fibrosis." (PMID 34161325, 2021). "Zhang's research revealed that 5 mg/kg hydroxysafflor yellow A attenuated liver fibrosis by downregulating TGF-β1, inhibiting phosphorylation of Smad4, and suppressing the ERK5 signaling pathways." (PMID 33082829, 2020). "Translocation of both linker and C-terminally phosphorylated Smad2 (pSmad2L/C) to the nucleus cooperates with pSmad3L and Smad4 to enhance PAI-1 transcription and promote hepatic fibrosis." (PMID 31991602, 2020). "Echinacoside, a natural phenol belonging to the phenylpropanoid class of caffeic acid glycosides, suppresses liver fibrosis in vivo by reducing the expression of TGF-β1, β-catenin, Smad4, MMP-9, PI3K, mTOR, cellular communication network factor 2 (CCN2), platelet-derived growth factor-B (PDGFB)." (PMID 40655154, 2025). "To examine whether Smad4 is involved in immune cell infiltration in the TME, we analyzed immunocyte profiles in CCl4-induced liver fibrosis and DEN/CCl4-induced HCC tissues." (PMID 39346534, 2024). "Here, our results indicated that Smad4 expression in hepatocytes could activate HSCs through improving CTGF secretion, and thereby promoted liver fibrosis." (PMID 36232998, 2022). "Smad4 is a core mediator of the TGF-β signaling pathway that can interact with Smad2/3 to transmit upstream Smad signals and promote the occurrence and development of liver fibrosis." (PMID 36232998, 2022). "The expression of TGF-β1, Smad2/3, p-Smad2/3, and Smad4 sharply increased as liver fibrosis progressed and peaked at 7 or 9 wpi, while the negative regulator Smad7 dramatically decreased at 9 wpi." (PMID 36474240, 2022). "Furthermore, the OEFL and its main bioactive substance, p-coumaric acid, alleviated liver fibrosis by downregulating TGF-β, SMAD-2, SMAD-4, α-SMA, and upregulating MMP-1." (PMID 35208964, 2022). "Furthermore, clinical investigation showed that CCAT2 and Smad4 expression level were significantly induced, while miR-34a-5p was significantly decreased in HBV related liver fibrosis serum." (PMID 36482069, 2022). "Consistently, we found that Smad4 deletion in hepatocytes alleviated EMT and preserved the expression of the epithelial marker, E-cadherin, which suggested that the absence of Smad4 in hepatocytes attenuated the development of liver fibrosis." (PMID 36232998, 2022).
liver fibrosis (continued). "Moreover, emodin also protected against liver fibrosis and HSC activation by reducing TGF-β1 and Smad4 expression and inhibiting tissue inhibitor of metalloproteinases-1 (TIMP-1) expression, and epithelial-mesenchymal transition." (PMID 33082829, 2020). "Furthermore, Smad-4 promotes fibrosis as a downstream mediator of TGF-β1, and hepatic fibrosis results from the inhibition of ECM degradation through specific tissue inhibitors of metalloproteinases." (PMID 24223741, 2013). "As illustrated in figure seven, B19 NS1 protein aggravates the hepatic fibrosis by enhancing the expression of TGF-β isoforms and activation of Smad2/3, which urge phosphorylated Smad2/3 to cooperate with Smad4 and Sp1 and induce the consequent fiboriss-related proteins, including PAI-1 and α-SMA." (PMID 23840852, 2013). "In a CCl4-induced liver fibrosis model, the deletion of Smad4 in hepatocytes resulted in suppressed ID1 expression and connective tissue growth factor (CTGF) secretion, subsequently activating the p38 and p65 signaling pathways in HSCs and thereby alleviating liver fibrosis." (PMID 39199400, 2024). "Molecularly, Smad4 expression in hepatocytes upregulated the expression of ID1 and further enhanced the paracrine activity of CTGF; subsequently, mediated by EGFR, CTGF promoted HSCs’ activation by regulating the p38 and p65 signaling pathways, which in turn led to liver fibrosis." (PMID 36232998, 2022). "With respect to the central role of SMAD4 in TGF- β /SMAD signal transduction, our aim of this study was to examine in vitro if SMAD4 may be a key molecule of TGF-β signaling pathway with a role in the pathogenesis of liver fibrosis." (PMID 26468346, 2015). "In addition, previous studies have indicated that anti-sense Smad4 gene could block TGF-β1 signal transduction by reducing the expression of Smad4 to inhibit the production of ECM and ameliorate hepatic fibrosis." (PMID 24685242, 2014). "Since the tendency of the expression of Smad4 was opposite to that of miR-454 in the process of hepatic fibrosis induced by S. japonicum infection, we hypothesized that miR-454 may be involved in the progression of liver fibrosis induced by S. japonicum infection through the TGF-β1/Smad4 pathway." (PMID 24685242, 2014).
ovarian carcinoma (52 papers, 2010 to 2025). A malignant neoplasm originating from the surface ovarian epithelium. "Higher expression of the SMAD4 protein was associated with a shorter overall survival (OS) of patients with ovarian cancer." (PMID 34205023, 2021). "In ovarian cancer, Smad4 level was reduced in cancer cells and loss of Smad4 in blood vessel endothelial cells facilitated cancer metastasis." (PMID 33372356, 2021). "Further, circATRNL1 inhibited ovarian cancer abdominal metastasis in vivo through miR‐378/Smad4, and low level of circATRNL1 was associated well with low survival rate of ovarian cancer." (PMID 33372356, 2021). "Together, our study reveals an essential role of circATRNL1/miR‐378/Smad4 in ovarian cancer and sheds light on the molecular mechanisms underlying ovarian cancer development." (PMID 33372356, 2021). "Our integrative approach revealed significant associations of TGFβ/SMAD4 regulatory networks with both progression free and overall survival in ovarian cancer patients." (PMID 21799915, 2011). "In addition, EVs released by epithelial ovarian cancer cell lines carrying SMAD4 mutations enhanced platinum-resistant phenotype in recipient drug-sensitive ovarian cancer cells, suggesting a possible transfer of SMAD4 mutations through EVs." (PMID 32384712, 2020). "Thus, this cell line is also an appropriate model system for carrying out genome-wide mapping of SMAD4 target genes and identifying the deregulated TGFβ/SMAD4 target genes and pathways implicated in ovarian cancer patients." (PMID 21799915, 2011). "The SMAD4 protein is an integral part of the TGFβ pathway, known to act as a transcriptional repressor of p21 in ovarian carcinoma cells." (PMID 37060086, 2023). "In the same cell types, compared with the DDP group, the expression of LC3II, Beclin1, TGF-β, and Smad4 proteins of ovarian cancer cells treated with DDP and transfected with miR-30a mimics was markedly down-regulated." (PMID 34747309, 2021). "Western blotting results suggested that 3-MA induced the down-regulation of TGF-β, LC3I/II, Beclin1, and Smad4 in ovarian cancer cells." (PMID 34747309, 2021). "Expression of miR-30a was significantly decreased, while expressions of TGF-β and Smad4 mRNA were increased in serum of ovarian cancer patients after DDP chemotherapy as well as in DDP-resistant cells." (PMID 34747309, 2021). "Human ovarian cancer tissues and cell lines were used to examine levels of circATRNL1, miR‐378, Smad4, AKT, and other proliferation‐related and migration‐related proteins." (PMID 33372356, 2021). "Here, we report that the expression of circATRNL1 is low in ovarian cancer cells, leading to increased miR‐378 levels and reduced levels of the downstream target Smad4." (PMID 33372356, 2021). "In the study, we showed that miR‐378 directly bound to Smad4 mRNA and circATRNL1/miR‐378 regulated ovarian cancer progression via Smad4 signaling." (PMID 33372356, 2021). "To further confirm the function of circATRNL1/miR‐378/Smad4 axis in ovarian cancer, we next studied how Smad4 affected the function of circATRNL1 in ovarian cancer." (PMID 33372356, 2021). "MiR-183 exerts tumor-promoting effects in ovarian cancer by regulating one of the transcription factor proteins, Mothers against decapentaplegic homolog 4 (Smad 4), via the TGF-β/Smad4 pathway." (PMID 34072593, 2021). "In ovarian cancer, previous studies showed that deletion of Smad4 in blood vessel endothelial cells facilitates ovarian cancer metastasis." (PMID 33372356, 2021). "Our findings indicate that circATRNL1 acts as a miR‐378 sponge to active Smad4 signaling and suppresses angiogenesis and ovarian cancer metastasis." (PMID 33372356, 2021). "circATRNL1 promoted ovarian cancer cell apoptosis but suppressed cancer cell proliferation, migration, and invasion, as well as angiogenesis, via targeting miR‐378/Smad4 signaling." (PMID 33372356, 2021).